BRSK1 (BR serine/threonine kinase 1)
Description:
Serine/threonine-protein kinase that plays a key role in polarization of neurons and centrosome duplication. Phosphorylates CDC25B, CDC25C, MAPT/TAU, RIMS1, TUBG1, TUBG2 and WEE1. Following phosphorylation and activation by STK11/LKB1, acts as a key regulator of polarization of cortical neurons, probably by mediating phosphorylation of microtubule-associated proteins such as MAPT/TAU at 'Thr-529' and 'Ser-579'. Also regulates neuron polarization by mediating phosphorylation of WEE1 at 'Ser-642' in postmitotic neurons, leading to down-regulate WEE1 activity in polarized neurons. In neurons, localizes to synaptic vesicles and plays a role in neurotransmitter release, possibly by phosphorylating RIMS1. Also acts as a positive regulator of centrosome duplication by mediating phosphorylation of gamma-tubulin (TUBG1 and TUBG2) at 'Ser-131', leading to translocation of gamma-tubulin and its associated proteins to the centrosome. Involved in the UV-induced DNA damage checkpoint response, probably by inhibiting CDK1 activity through phosphorylation and activation of WEE1, and inhibition of CDC25B and CDC25C.
Synonyms: hSAD1; KIAA1811; SAD-B
Tractability: Small molecule: a high-quality ligand is known; it belongs to a druggable protein family. PROTAC: its protein half-life has been measured; a small molecule that binds it is known.
Target class: CAMK protein kinase group; Protein Kinase; Enzyme; CAMK protein kinase BRSK subfamily; CAMK protein kinase CAMK1 family; Kinase
Gene: Protein-coding gene on chromosome 19 (55,282,072 to 55,312,562, forward strand). Ensembl gene ENSG00000160469.
Subcellular location: Cytoplasm; Nucleus; Cytoplasm, cytoskeleton, microtubule organizing center, centrosome; Synapse; Presynaptic active zone; Cytoplasmic vesicle, secretory vesicle, synaptic vesicle
Subcellular location (Human Protein Atlas): Nucleoplasm; Plasma membrane; Vesicles
Gene Ontology:
Molecular function: magnesium ion binding; protein serine/threonine kinase activity; tau-protein kinase activity; ATP binding; gamma-tubulin binding; tau protein binding; protein kinase activity; protein kinase binding; protein serine kinase activity
Biological process: DNA damage response; G2/M transition of mitotic cell cycle; mitotic G2 DNA damage checkpoint signaling; peptidyl-serine phosphorylation; protein phosphorylation; response to ionizing radiation; response to UV; associative learning; axonogenesis; centrosome duplication; establishment of cell polarity; microtubule cytoskeleton organization involved in establishment of planar polarity; neuron differentiation; neurotransmitter secretion; regulation of axonogenesis; regulation of neuron projection development; regulation of synaptic plasticity; regulation of synaptic vesicle clustering; synaptic vesicle cycle; regulation of synaptic vesicle priming
Cellular component: cytoplasm; nucleoplasm; nucleus; centrosome; distal axon; presynaptic active zone; synapse; synaptic vesicle; cholinergic synapse; postsynaptic density
Genetic constraint (gnomAD): Loss-of-function variants: 16 observed, 81.33 expected, observed/expected ratio (o/e) 0.2, 90% interval 0.13 to 0.3. The upper end of that interval is the gene's LOEUF score, 0.3, which puts it in group 1 of 6, group 1 being the genes least tolerant of losing a copy. Missense variants: 684 observed, 1,012.4 expected, observed/expected ratio (o/e) 0.68, 90% interval 0.63 to 0.72. Synonymous variants: 447 observed, 411.3 expected, observed/expected ratio (o/e) 1.09, 90% interval 1 to 1.17.
Homologues: Orthologues: macaque BRSK1 (100% identical), mouse Brsk1 (99% identical), rat Brsk1 (99% identical), chimpanzee BRSK1 (97% identical), dog BRSK1 (96% identical), guinea pig BRSK1 (95% identical), pig BRSK1 (90% identical), tropical clawed frog brsk1 (80% identical), rabbit BRSK1 (54% identical), Drosophila melanogaster Nuak (23% identical), Drosophila melanogaster Snrk (18% identical), Caenorhabditis elegans ZK524.4 (17% identical), and 3 more. Paralogues in human: BRSK2 (72% identical), SIK2 (26% identical), SIK3 (26% identical), SIK1 (25% identical), MELK (22% identical), PRKAA1 (22% identical), NUAK2 (21% identical), PRKAA2 (21% identical), SNRK (21% identical), HUNK (20% identical), NUAK1 (20% identical), NIM1K (15% identical), and 5 more.
Diseases named in the same sentence as BRSK1 in open-access papers:
BRSK1 is named in the same sentence as 24 diseases in open-access papers, as found by Europe PMC text mining. Sharing a sentence is not in itself a finding about the gene and the disease. The quoted sentences say what the papers report.
breast carcinoma (3 papers, 2013 to 2025). "Nuclear YAP/TAZ drives breast cancer cell proliferation, and concordantly, siRNA mediated abrogation of BRSK1 expression suppressed the growth of MDA-MB231 cells." (PMID 40869130, 2025). "In all breast cancer combined, high expression of LKB1, AMPK, LYK5, MARK1, MARK2, NUAK2, PAK1 (both probe sets), SIK1, SIK2, BRSK1, BRSK2, SNRK, and QSK was positively correlated with improved survival compared to low expression of these genes." (PMID 34084284, 2021). "In Luminal A breast cancers, the positive survival effects of AMPK, MARK3, PAK1, BRSK1, SNRK, and QSK are maintained in the pre-chemotherapy but not in the post-chemotherapy cohorts." (PMID 34084284, 2021).
autism (1 paper, 2023). Persistent deficits in social interaction and communication and interaction as well as a markedly restricted repertoire of activity and interest as well as repetitive patterns of behavior. "However, when we queried the SFARI Gene database, which tracks the ever-expanding genetic risk factors of autism, surprisingly, we found that BRSK1 has not yet been included among the autism risk genes." (PMID 37671287, 2023).
glioma (1 paper, 2018). A benign or malignant brain and spinal cord tumor that arises from glial cells (astrocytes, oligodendrocytes, ependymal cells). "Some intriguing aspects of the core gene set identified in this study include the well-studied glioma-related genes ANGPT2, CD44, SPP1, STAT3, PDGRFA, and TOP2A (all up-regulated), and BRSK1, DKK3, FGFR2, MAPK9, MEF2C, and PTEN (all down-regulated)." (PMID 29352201, 2018).
lung large cell carcinoma (1 paper, 2022). A poorly differentiated non-small cell lung carcinoma composed of large polygonal cells without evidence of glandular or squamous differentiation. "BRSK1 was reported to be a biomarker for lung large cell carcinoma with a role in LKB1 signaling)." (PMID 35571016, 2022).
Premature ovarian insufficiency (1 paper, 2021). Amenorrhea due to loss of ovarian function before the age of 40. "So far, large-scale GWAS have identified several SNPs, such as rs11668344 (BRSK1), rs365132 (UIMC1) and rs16991615 (MCM8), relevant for age at natural menopause or premature ovarian insufficiency (POI) in the general population." (PMID 34572825, 2021).
cancer (5 papers, 2013 to 2025). A tumor composed of atypical neoplastic, often pleomorphic cells that invade other tissues. "In particular, the expression of secretion-related genes (e.g., BNDF, BRSK1, and Ccnd1) in the gastrocnemius muscle during high-intensity aerobic exercise suggests their potential role in cancer suppression." (PMID 35801156, 2022). "Other understudied kinases that score favorably in the majority of cancer cohorts include PKMYT1 (Tchem), DCLK3 (Tchem), BRSK1 (Tchem), ADCK5 (Tdark), and LMTK3 (Tbio)." (PMID 33205077, 2020).
tumor (2 papers, 2022 to 2023). "The downstream LKB1 signaling factors SIK2 and BRSK1/2 did not appear to be mediated by the tumor scaffold compared to TCP." (PMID 35755802, 2022).
BRSK1 also shares sentences with these, for which no sentence is quoted: temporal lobe epilepsy (2 papers); colorectal adenoma (1); developmental delay (1); epilepsy (1); hepatocellular carcinoma (1); infection (1); leukemia (1); lymphoma (1); melanoma (1); myeloma (1); nervous system diseases (1); osteoarthritis (1); pancreatic cancer (1); premature ovarian failure (1); rectum cancer (1); schizophrenia (1); viral infection (1).